TLR3 (toll like receptor 3)
Diseases named in the same sentence as TLR3 in open-access papers (continued):
Sharing a sentence is not in itself a finding about the gene and the disease.
COVID-19 (continued). "In summary, our research indicated that patients with an unfavorable outcome presented lower TLR3 expression and enhanced expression of TLR4 which may be a compensatory mechanism that leads to a prominent inflammatory response that is characteristic of severely ill COVID-19 patients." (PMID 34315957, 2021). "Several studies have suggested the role of TLRs in enhancing humoral responses during COVID-19 infection, but so far, no study has examined the expression of TLR3, TLR7, TLR8 and TLR9 on respiratory epithelial cells from COVID-19 patients." (PMID 35538443, 2022). "There was no significant upregulation of TLR3, TLR7, TLR8, and TLR9 in the epithelial cells from COVID-19-Group C compared to Control-Group I, Control-Group II, and Control-Group III." (PMID 35538443, 2022). "In the current investigation, we determined the expression levels of TLR3, TLR7, TLR8, and TLR9 in the epithelial cells obtained from confirmed COVID-19 cases with and without different clinical symptoms." (PMID 35538443, 2022). "TLR1, TLR4, TLR5, TLR8, and TLR9 expression levels were also significantly elevated in severe and critical COVID-19 patients; however, TLR3 expression was not correlated with the development of COVID-19, and an increased expression of TLR7 was observed only in patients with moderate COVID-19." (PMID 34835108, 2021). "Third, we observed that the SARS-CoV-2 M protein specifically inhibits RIG-I/MDA-5–MAVS signaling rather than TLR3–TRIF or cGAS–STING signaling, a finding that may suggest more precise therapeutic targets for COVID-19." (PMID 33372174, 2020).
breast carcinoma (88 papers, 2008 to 2026). "have linked a specific single nucleotide polymorphism (SNP) in the TLR3 promoter region (rs5743305) with an increased risk of breast cancer, suggesting the role of TLR3 as a tumor suppressor gene." (PMID 38903515, 2024). "Bioinformatic analysis using high-throughput RNA-sequencing data from the TCGA demonstrated that the reduced expression of TLR3 in breast cancer was associated with advanced clinicopathological characteristics, survival time, and poor prognosis." (PMID 37005579, 2023). "Logistic regression showed that TLR3 expression was associated with distant metastasis (stage 4 breast cancer)." (PMID 37005579, 2023). "Bioinformatic analysis using high-throughput RNA-sequencing data from TCGA and METABRIC demonstrated that the reduced expression of TLR3 in breast cancer was associated with survival time, and poor prognosis." (PMID 37005579, 2023). "IFN-λ1 production by cDC1, proposed to be via TLR3, has recently been associated with positive clinical outcomes and local Th1 immune responses in breast cancer patients." (PMID 35281062, 2022). "TLR3 polymorphisms have also been linked to an increased risk of several cancers such as nasopharyngeal carcinoma, breast cancer, cervical cancer, and Hodgkin’s disease." (PMID 33679703, 2020). "In this present study, we sought to extend our earlier observations of TLR3 and Wnt5a association and their role in tumor viability/growth and migration in human breast cancer." (PMID 29371911, 2017). "In breast cancer, tumors with a high expression of TLR3 were associated with a significantly greater probability of metastasis." (PMID 28438134, 2017). "In conclusion, this study has shown for the first time that the TLR3 SNP rs3775291 is associated with an increased risk of relapse in breast cancer, especially for the luminal B, TNBC, and HER2+ subtypes." (PMID 26226228, 2015). "This suggests that TLR3 activation uniquely associates with CSC-like properties in breast cancer cell SUM190." (PMID 25257174, 2015). "Besides, the SNP of the TLR3 gene at rs5743305 are suggested to be linked to increased breast cancer risk, whereas the SNP of the TLR3 gene at rs3775291 are reportedly linked to breast cancer recurrence." (PMID 37593100, 2023). "In support of this, polymorphisms in TLR genes or TLR expression have been found associated with these cancers; for instance, in breast cancer, polymorphisms in TLR3, 5, and 9 genes may either increase breast cancer risk or play protective roles." (PMID 36765715, 2023). "Notably, activation of TLR3 on human breast cancer-associated dendritic cells has been shown to increase IFN-λ production which in turn directed IL-12 release." (PMID 34124272, 2021). "Here, we hypothesized that genetic variants in TLR1 and TLR3 may be associated with breast cancer outcome." (PMID 26226228, 2015). "Along similar lines, TLR3 SNPs have been associated with an altered risk for cervical cancer amongst 330 Tunisian women, breast carcinoma amongst 174 African-American women, oral squamous cell carcinoma amongst 197 individuals HCC amongst 948 subjects, and CRC amongst more than 5,000 individuals." (PMID 26300886, 2015). "In addition, treatment with double-stranded RNA (dsRNA) has been shown to be associated with a significant decrease in the risk of relapse in TLR3-positive breast cancer." (PMID 26226228, 2015). "Given that poor clinical prognosis was associated with elevated TLR3 expression in breast cancer, it is possible that tumor cells with high levels of TLR3 expression and activation of NF-κB and Wnt/β-catenin pathways are more resistant to conventional therapies and easy to relapse." (PMID 25257174, 2015). "This pilot study of immunogenicity of a TLR3 agonist in combination with helper T cell stimulation as adjuvants to traditional class I peptides showed that novel adjuvants can be safely combined with multi-peptide vaccines in the high risk breast cancer setting." (PMID 29157306, 2017).
breast carcinoma (continued). "CLEC2D is induced by TLR3/4/7/8/9 ligands in immune cells, and these TLRs are also expressed in breast cancer cells." (PMID 40938562, 2026). "Activation of TLR3 has been shown to increase cancer stem cell (CSC) markers, which are associated with breast cancer progression." (PMID 40631077, 2025). "On the other hand, earlier reports also showed that TLR3 signaling directly or indirectly induces apoptosis in gastric cancer, colon cancer, breast cancer, prostate cancer, ovarian cancer, hepatocellular carcinoma and head and neck cancer cells." (PMID 40029556, 2025). "In this study, we investigate for the first time the ability of GEN to enhance TLR3-mediated signaling in MCF-7 and MDA-MB-231 breast cancer cells, both alone and in combination with Poly I:C, a synthetic TLR3 agonist." (PMID 40844548, 2025). "Our results further support these conclusions, while in other studies, activation of TLR3 promotes the transformation of breast cancer cells to cancer stem cells, leading to the acquisition of stem cell properties." (PMID 38738791, 2024). "The context-dependent roles of TLR3 in breast cancer are influenced by various factors including cancer stage, tumor microenvironment, and specific signaling pathways activated." (PMID 38903515, 2024). "These exosomes, induced by TLR3, demonstrate the ability to induce immunogenic cell death specifically in breast cancer cells, highlighting their potential in therapeutic interventions." (PMID 38903515, 2024). "Further investigations revealed that TLR3 activation, particularly by synthetic ligands like poly(I:C), inhibits breast cancer cell growth and induces apoptosis, thus suppressing tumor growth and metastasis in mouse models." (PMID 38903515, 2024). "Harnessing the immunostimulatory properties of TLR3 while mitigating its pro-tumorigenic effects holds promise for targeted therapies against breast cancer." (PMID 38903515, 2024). "We found that TLR3 acts as a suppressor gene in breast cancer initiation and progression in our previous two-stage association studies and functional investigations." (PMID 37005579, 2023). "The high TLR3 expression breast cancer tissues had a high fraction of resting CD4 memory resting T cells (p < 0.001), resting Mast cells (p < 0.001), and M1 Macrophages (p < 0001)." (PMID 37005579, 2023). "A Kaplan–Meier plotter revealed that TNBC with high TLR3 expression had a better prognosis than breast cancer with low TLR3 expression (p = 0.042) in the FUSCC TNBC cohort." (PMID 37005579, 2023). "TLR3 is expressed not only in immune system cells, such as dendritic cells and macrophages, but also in other cells, such as epithelial, fibroblast, and breast cancer cells." (PMID 37005579, 2023). "TLR3 usually functions as a tumor suppressor gene, and studies in prostate cancer and breast cancer showed that TLR3 can inhibit apoptosis, and TLR3 positive patients have a lower risk of metastasis." (PMID 37283287, 2023). "We have previously reported that Toll-like receptor 3 (TLR3) acts as a suppressor gene for breast cancer initiation and progression." (PMID 37005579, 2023). "The aim of the current study was to evaluate the prognostic value of TLR3 expression in human breast cancer." (PMID 37005579, 2023). "Previous studies found that TLR3 is a biomarker for the therapeutic efficacy of double-stranded RNA in breast cancer." (PMID 37005579, 2023). "Immunohistochemical staining of the tissue microarrays showed that TLR3 had lower expression in breast cancer tissues than in the adject normal tissues." (PMID 37005579, 2023). "TLR3 plays a negative regulatory role in the initiation and progression of human breast cancer cells, at least in part by downregulating the EGFR/PI3K/AKT pathway." (PMID 37005579, 2023). "TLR3 expression in breast cancer and normal tissues were compared, and the results indicated that TLR3 expression was lower in breast cancer than in the normal controls (p = 2.52 × 10–39)." (PMID 37005579, 2023).
breast carcinoma (continued). "One study loaded an ICD inducer, human neutrophil elastase (ELANE), and a TLR3 agonist Hiltonol onto breast cancer-derived Tu-sEVs to form an in situ vaccine (HELA-sEVs)." (PMID 37681880, 2023). "We first observed that breast cancer patients with high TLR3 expression had a better prognosis using the Kaplan–Meier plotter (P = 0.0015)." (PMID 37005579, 2023). "HELA-sEV-induced ICD of breast cancer cells followed by TLR3 adjuvant-induced i.t. accumulation of cDC1s and cross-primed immunogenic CD8+ T cell responses." (PMID 37681880, 2023). "The high TLR3 expression breast cancer tissues had a low fraction of M0 Macrophages, regulatory T cells (p < 0.001), and plasma cells (p < 0.001)." (PMID 37005579, 2023). "The activation of TLR3 using a poly (I:C) glycopeptide vaccine induced a pro-inflammatory environment and elicited a strong cellular immune response crucial for breast cancer elimination." (PMID 37005579, 2023). "Immunohistochemical staining of tissue microarrays showed that TLR3 had lower expression in breast cancer tissues than in the adject normal tissues." (PMID 37005579, 2023). "The findings displayed that the poly(I:C)-conjugated NPs were effectively aimed at breast cancer cells (owing to a dsRNA/TLR3 interaction)." (PMID 37238916, 2023). "In fact, there several clinical trials focusing the tumor vaccines based on TLR3 agonists have conducted in colorectal cancer, melanoma, breast cancer, and prostate cancer." (PMID 35000541, 2022). "We also found that pharmacological inhibition of TLR3 abolished breast cancer-induced HAO1 expression and oxalate production." (PMID 35739335, 2022). "We loaded the immunogenic cell death (ICD) inducers human neutrophil elastase (ELANE) and Hiltonol (TLR3 agonist) into α-lactalbumin (α-LA)-engineered breast cancer-derived exosomes to form an in situ DC vaccine (HELA-Exos)." (PMID 35148751, 2022). "TLR3 stimulation is a potent strategy to induce the activation and maturation of cDC1s in the breast cancer TME." (PMID 35148751, 2022). "TLR3 stimulation can trigger coactivation of NF-κB and β-catenin, which promote breast cancer cells to acquire a CSC phenotype in vivo and in vitro." (PMID 33986756, 2021). "TLR3 expressed by human and mouse breast cancer cells promotes apoptosis by inducing type I IFN signaling." (PMID 33747948, 2021). "In an in vitro study, activation of TLR3 by dsRNA can trigger apoptosis in human breast cancer cells, which involves Toll/IL-1R domain-containing adaptors that induce IFN-β and type I IFN autocrine signaling, as well as activation of extrinsic caspases." (PMID 33986756, 2021). "TLR3 was reported to be expressed not only by immune cells but also in the various cancer cells, such as breast cancer, prostate cancer, epithelial adenocarcinoma, and others." (PMID 33072559, 2020). "We had previously reported the surface localization of TLR3 and its proliferative effect on breast cancer cells." (PMID 33072559, 2020). "Induction of cell proliferation via surface localization of TLR3 has been shown by our research group in breast cancer cells and by other groups in diverse types of cancers." (PMID 33072559, 2020). "Stimulation of TLR3 in cancer cells directly induced apoptosis and TLR3 expression in breast cancer patients has been reported to predict clinical responses to TLR3 ligand stimulation." (PMID 33036630, 2020). "Further, cell surface expression of TLR3 has been reported in a variety of cells such as pulmonary cells, hepatocytes, breast cancer, prostate cancer, and epithelial adenocarcinoma indicating that its signaling occurs through the plasma membrane." (PMID 33072559, 2020). "The TLR3 agonist Poly (I:C) reportedly suppressed tumor growth in mice, and TLR3 agonists have been assessed in phase I/II trials as adjuvants for therapeutic vaccination against melanoma and breast cancer." (PMID 32377528, 2020).
breast carcinoma (continued). "We have shown in our initial experiments that exogenous stimulation of TLR3 by its ligand promotes cellular proliferation in breast cancer cells." (PMID 33072559, 2020). "In breast cancer cell lines, it has been shown that TLR3, once stimulated with its ligand Poly(I:C), leads to Stat1 phosphorylation and strong TRIF-dependent production of IFN-β, together with NF-κB activation and release of pro-apoptotic cytokines." (PMID 33147700, 2020). "Overall, this study provides first comprehensive evidence on the involvement of canonical signaling of TLR3 using MyD88–cyclin D1-mediated breast cancer cell proliferation." (PMID 33072559, 2020). "We recruited 12 female patients with stage 1, 2, or 3 breast cancer and matured their DCs with autologous tumour-specific lysate, a toll-like receptor (TLR)-3 and 7/8 agonist, and an interferon-containing cocktail." (PMID 30283982, 2019). "It has been recently demonstrated that stimulation of TLR3 by poly(I:C) promotes breast cancer cells toward a CSC phenotype in vitro and in vivo, thus potentiating cancer recurrences." (PMID 30112117, 2018). "Recent studies have highlighted the important pathologic role of TLR3 and Wnt5a in progression, sustenance and metastasis of breast cancer." (PMID 29371911, 2017). "In these studies we sought to evaluate the effect of the same TLR signaling inhibitor, C10, on human MCF-7 breast cancer cells that exhibit high constitutive levels of TLR3 and Wnt5a RNA." (PMID 29371911, 2017). "A vaccine consisting of 9 MHC class I-restricted breast cancer-associated peptides (from MAGE-A1, −A3, and -A10, CEA, NY-ESO-1, and HER2 proteins) was combined with a TLR3 agonist, poly-ICLC, along with a helper peptide derived from tetanus toxoid." (PMID 29157306, 2017). "TLR3 and -4 were identified as predictors of poor survival in breast cancer, whereas high TLR9 predicted enhanced survival." (PMID 27941651, 2016). "have previously shown the predictive value of TLR3 expression in the response of breast cancer patients to dsRNA-based treatment." (PMID 25444175, 2015). "Unexpectedly, β-catenin pathway is required for the promotion of CSC phenotypes in breast cancer cells following TLR3 activation." (PMID 25257174, 2015). "Several lines of evidence have indicated that TLR3 plays important roles in breast cancer development and progression." (PMID 26226228, 2015). "Along similar lines, TLR3 expression levels have been shown to predict the response of 194 breast carcinoma patients treated with adjuvant radiotherapy plus a TLR3 agonist." (PMID 26300886, 2015). "Here, we demonstrate that TLR3 activation in breast cancer cells leads to a preferential enrichment of a subset of cells with CSC phenotypes in vitro and in vivo." (PMID 25257174, 2015). "Here, we demonstrate that stimulation of toll-like receptor 3 (TLR3) promotes breast cancer cells toward a CSC phenotype in vitro and in vivo." (PMID 25257174, 2015). "This study provides evidence of an antitumoral mechanism of action upon TLR3 activation and the biological rationale for a combined TLR3 agonist/retinoic acid treatment of prostate and breast cancer." (PMID 25881300, 2015). "To exclude the possibility that TLR3 activation is breast cancer cell-type specific, we also examined the breast ductal carcinoma cell line BT-483, adenocarcinoma cell line Cama-1 and triple-negative inflammatory breast cancer cell line SUM149." (PMID 25257174, 2015). "The predictive value of TLR3 expression by tumor cells for the efficacy of Poly (A : U) dsRNA was determined in 194 breast cancer patients enrolled in a randomized clinical trial." (PMID 22295250, 2012). "Samples of mammary carcinomas with recurrence have also exhibited a significant increase in the mRNA levels of TLR3, TLR4, and TLR9." (PMID 22295250, 2012). "TLR3 overexpression has been reported in a number of human malignancies, such as melanoma, breast cancer, clear cell carcinoma, neuroblastoma, or head and neck squamous cell cancer." (PMID 23198710, 2012).